SIRT1 (sirtuin 1)
Diseases named in the same sentence as SIRT1 in open-access papers (continued):
Sharing a sentence is not in itself a finding about the gene and the disease.
diabetes (continued). "Similarly, in cardiac MECs, miR-195 expression is increased in response to streptozotocin-induced diabetes, which is associated with reduced SIRT1 levels, impaired myocardial function, oxidative stress, and myocardial hypertrophy, whereas silencing of miR-195 reverses these effects." (PMID 39598406, 2024). "Moreover, AMPK/SIRT1 signaling has been implicated in the pathogenesis of diabetes." (PMID 38919261, 2024). "In the development of diabetes and diabetic nephropathy, various cell stress factors may directly cause cellular senescence or down-regulate anti-aging proteins (e.g., Sirt1 and Klotho) and indirectly cause cellular senescence; however, the specific mechanism remains to be elucidated." (PMID 36359836, 2022). "Besides, several studies have reported that the enhancement of SIRT1 expression after melatonin treatment could alleviate diabetes-associated cardiovascular complications by reducing apoptosis and oxidant stress." (PMID 34336116, 2021). "Therefore, alterations in SIRT1 gene expression may be associated with the pathogenesis of diabetes and its complications." (PMID 34656137, 2021). "Overall, diabetes-induced downregulation of sirtuins (SIRT1, 3 and 6) appears to promote oxidative stress and endothelial dysfunction, and induce cellular fibrosis, suggesting these molecules to be of potential therapeutic use in diabetes and associated vascular complications." (PMID 29085333, 2017). "Together, anddespite the lack of effect on longevity, our results demonstrate a beneficialrole for Sirt1 in liver damage, metabolic syndrome-associated liver cancer, andin a variety of aging-associated pathologies, such as spontaneous carcinomasand sarcomas, diabetes and osteoporosis." (PMID 20562473, 2010). "Given its role in major diseases such as diabetes, neurodegeneration, cardiovascular disorders, and cancer, identifying novel SIRT1 modulators remains a major therapeutic focus." (PMID 41304625, 2025). "In patients with type 2 diabetes mellitus, resveratrol enhanced the expression of SIRT1, thereby improving the osteogenic potential of bone marrow MSCs." (PMID 40243497, 2025). "Another study investigated the role of SRT204 in male diabetic mice, where it enhanced the production of the SIRT1 protein, alleviating ER stress and ameliorating diabetes-induced oxidative damage." (PMID 41567643, 2025). "Diabetic neuropathy is a complex and debilitating complication of diabetes, marked by reduced expression of Sirt1, a protein that plays a crucial role in cellular stress responses and metabolic regulation." (PMID 40958722, 2025). "In tissue repair, exosomes combined with the diabetes drug metformin use the AMPK/SIRT1 pathway to rebuild damaged liver mitochondria." (PMID 41268687, 2025). "Understanding the intricate interplay between miR-200a-3p and SIRT1 in the context of tubular damage holds promise for the development of novel therapeutic strategies aimed at mitigating renal injury in HTN and diabetes-associated renal damage." (PMID 40723868, 2025). "Both S1P-related signaling and SIRT1 are involved in regulating inflammatory processes, which are evident during the progression of diabetes and its complications, especially in the brain, and have drastic consequences on its proper functioning." (PMID 41301404, 2025). "Numerous studies highlight the crucial role of the brain SIRT1 signaling pathway in the development of insulin-resistance-related cognitive deficits in animal models of diabetes." (PMID 41301404, 2025). "This study seeks to systematically examine blood concentrations and gene expression of CD38, NAMPT, and SIRT1 across several stages of albuminuria in individuals with type 2 diabetes mellitus." (PMID 41470091, 2025).
diabetes (continued). "The concentration of sirtuin 1 in patients with diabetes has been extensively investigated in previous studies." (PMID 41009597, 2025). "Patients with concomitant diabetes had significantly lowered serum SIRT1 concentrations (Me = 2.4 [1.6–4.8] vs. Me = 3.3 [2.1–7.4] ng/mL, p < 0.05)." (PMID 41009597, 2025). "These discoveries highlight the AMPK/SIRT1/PGC‐1α system as a key controller of diabetes development, presenting new treatment possibilities that target insulin function, sugar processing, and fat regulation through precise pathway adjustments." (PMID 41268687, 2025). "The Cdk5-NGF/Sirt1 axis plays an important role in the damage of islet β cells in diabetes and is a new potential target for the treatment of diabetes." (PMID 41181709, 2025). "Therefore, Sirt1 agonists and bromodomain inhibitors may emerge as therapeutic strategies for diabetic nephropathy and could potentially offer new treatment directions for other organ damage caused by diabetes." (PMID 40337513, 2025). "During calorie restriction, increased expression of SIRT1 occurs that contributes to delaying the onset of diseases of aging such as diabetes, atherosclerosis, and cancer." (PMID 39980831, 2025). "Our previous study reported that MSC‐derived exosomes alleviated diabetes‐related muscle atrophy via SIRT1‐mediated mitochondrial function." (PMID 41383117, 2025). "Sustained miR-34a expression in diabetes accelerates endothelial dysfunction by repressing SIRT1-mediated antioxidant responses." (PMID 40864768, 2025). "The study found that RV supplementation positively influenced oxidative stress markers and sirtuin 1 levels, suggesting benefits for older adults managing diabetes." (PMID 40563357, 2025). "Our previous study showed that MSC‐derived exosomes alleviate diabetes‐induced muscle atrophy by improving SIRT1‐mediated mitochondrial function." (PMID 41383117, 2025). "The study found that resveratrol supplementation positively influenced oxidative stress markers and sirtuin 1 levels, suggesting benefits for older adults managing diabetes." (PMID 40563357, 2025). "Another is miR-34a, which has been related to diabetes, and to apoptosis and podocyte injury in DN through targeting SIRT1." (PMID 41233312, 2025). "Dapagliflozin, a SGLT2 inhibitor and sirtinol, a SIRT1 inhibitor, were used to investigate the role of the SGLT2-SIRT1 pathway in AF in a streptozotocin (STZ)-induced diabetes mellitus." (PMID 41516053, 2025). "NMN also helps maintain healthy metabolism in diabetes by preventing the usual drop in SIRT1 and PGC‐1α activity, using its protein‐modifying power to shield against high blood sugar damage." (PMID 41268687, 2025). "Sirtuin 1 (Sirt1) is a NAD+-dependent deacetylase, which is an important antioxidant enzyme associated with the development of diabetes mellitus." (PMID 40217882, 2025). "SIRT1, an NAD+-dependent deacetylase, complements AMPK by enhancing mitochondrial function and improving metabolic disorders associated with diabetes." (PMID 40458823, 2025). "To verify the expression levels of NGF and Sirt1 in the pancreatic islets, we analysed pancreatic tissues from clinically diagnosed patients with diabetes via immunohistochemical and immunofluorescence staining." (PMID 41181709, 2025). "SIRT1 is also involved in the pathogenesis of chronic conditions such as diabetes, pulmonary diseases, neurodegenerative diseases, and cardiovascular diseases." (PMID 40943481, 2025). "As has been noted, most antidiabetic drugs stimulate the expression of SIRT1 and hold therapeutic promise for diabetes mellitus; however, it should also be carefully considered that some of these interactions can have limitations or side effects." (PMID 39861104, 2025). "SIRT1 expression was found to be low in mice with STZ-induced diabetes, but puerarin increased SIRT1 expression, inhibited the activation of the NLRP3/caspase 1 pathway, reduced podocyte pyroptosis, and alleviated their renal inflammatory injury." (PMID 41020857, 2025).
diabetes (continued). "In diabetes mellitus, SIRT1-mediated ferroptosis plays an important role in islet β-cell dysfunction." (PMID 40109363, 2025). "Sirt1 is a potent positive regulator of autophagy, but its expression is often suppressed in the kidneys of various animal models of diabetes." (PMID 40337513, 2025). "Its regulatory influence on key chronic conditions, including diabetes, neurodegenerative, cardiovascular diseases, and tumorigenesis, makes SIRT1 a significant therapeutic target." (PMID 41304625, 2025). "SIRT1 reduces diabetes‐induced renal injury by synergistically working together through FOXO1‐mediated oxidative stress and autophagy." (PMID 40008520, 2025). "Flavonoids work similarly—hesperidin activates AMPK/SIRT1 to help with liver inflammation, regulate mitochondria in fatty liver disease, and improve diabetes‐related problems." (PMID 41268687, 2025). "SIRT1 can improve vascular function in diabetes by deacetylating the 66-kDa Src homology 2 domain-containing protein (p66Shc) and reducing ROS production." (PMID 38645427, 2024). "There is growing evidence supporting the cytoprotective role of SIRT1 in diabetes and its complications." (PMID 37695462, 2024). "In diabetes, SIRT1 enhances insulin sensitivity by deacetylating insulin receptor substrate 2 (IRS2), which boosts the insulin regulatory pathway." (PMID 38931292, 2024). "The role of Sirtuin 1 in diabetes is well-established; it acts as a protective factor for pancreatic β-cells and promotes glucose-dependent insulin release." (PMID 39944232, 2024). "Research has shown that one month after the onset of diabetes in rats, SIRT1 expression in cardiac tissue increases, while after three months, SIRT1 levels decrease." (PMID 39944232, 2024). "Human clinical studies targeting patients with coronary heart disease and type 2 diabetes mellitus have revealed that RES intake increased SIRT1 levels in the blood." (PMID 38792610, 2024). "Among seven Sirt isoforms, we have previously revealed the role of Sirtuin1 (Sirt1), an Sirt isoform, in diabetic nephropathy (DN), which is a diabetes-induced kidney damage, by assessing Sirt1-gene-engineered mice." (PMID 38587753, 2024). "A clinical trial reported that the ingestion of 500 mg RES for 4 weeks resulted in an increase in blood SIRT1 expression as a metabolic regulatory marker in patients with type 2 diabetes mellitus and coronary heart disease." (PMID 38792610, 2024). "Application of RSV reverses SIRT1 deactivation along with NF-κB activation, indicating a potential relationship between SIRT1 deactivation and NF-κB activation in the regulation of diabetes-induced retinal inflammation." (PMID 38716357, 2024). "A significantly lower frequency of the SIRT1 CC genotype in all diabetic patients (27.3%, p < 0.001) than in controls (36.7%) indicated its protective role against diabetes." (PMID 39474345, 2024). "Studies have reported that SIRT1 improved glucose and lipid metabolism in diabetes by regulating PGC-1α." (PMID 39596482, 2024). "LIR mitigates diabetes-induced bone metabolism imbalance by inhibiting NETs formation through SIRT1 mediation." (PMID 40066121, 2024). "Numerous studies have confirmed that SIRT1 plays an important role in slowing the development of neurodegenerative diseases and that SIRT1 is closely related to diabetes and cardiovascular diseases; thus, SIRT1 is also known as a longevity gene." (PMID 39531447, 2024). "Activation of retinal micro-endothelial SIRT1 via fasting or fasting-mimicking treatment also improves retinal cholesterol export, decreases retinal cholesterol, and diabetes-induced retinal inflammation to improve retinal function." (PMID 39598406, 2024). "miR-93 has also been shown to target SIRT1 in rats with streptozotocin-induced diabetes, thereby contributing to changes indicative of oxidative stress and inflammation, which can be reversed by SIRT1 overexpression." (PMID 38202299, 2024).
diabetes (continued). "Icariin modulation in endoplasmic reticulum stress and the stimulation of NO synthase through the PPARα/Sirt1/AMPKα pathway can significantly improve vascular endothelial function in diabetes, which seems to be a key mechanism of IR." (PMID 39768147, 2024). "Therapeutic strategies that target SIRT1 activity have shown promise in increasing insulin sensitivity and glycemic control in diabetes." (PMID 38931292, 2024). "Resveratrol can restore pancreatic β cells by inhibiting p38/p16MAPK pathway through SIRT1-dependent pathway, thus effectively improving ethanol-induced diabetes." (PMID 39872318, 2024). "Sirt1 levels can be reduced in chronic diseases such as diabetes, thus an increase in its expression is crucial for improving glucose indices and mitochondria function." (PMID 36835539, 2023). "Our translational findings demonstrate the central role of Sirt1 in maintaining cardiac homeostasis and modulating the myocardial lipidome in the context of diabetes." (PMID 37957697, 2023). "Then, we outline the role of SIRT1 in endocrine and metabolic diseases such as hyperuricemia, diabetes, hypertension, hyperlipidemia, osteoporosis, and polycystic ovarian syndrome." (PMID 36632457, 2023). "As a result, we showed that angiogenesis, NOX4 and SIRT1 protein levels decrease in the cardiac tissue in the early stage of diabetes." (PMID 36721814, 2023). "We further examined SIRT1 tissue levels in human arteries and found reduced vascular levels of the protein in patients with diabetes." (PMID 37401647, 2023). "It has been reported that AMPK/SIRT1 signaling plays an important role in the development of diabetes." (PMID 37723077, 2023). "Resveratrol, a GPER agonist, has been shown to counteract the effects of diabetes by increasing the activity and expression of Sirt1 and Sirt3 in the heart and improving cardiac mitochondrial function." (PMID 38134189, 2023). "The overexpression of histone gene Hist1-h1c along with the Sirt1 gene has also been correlated to the development of diabetes, which is a common condition secondary to DS." (PMID 37740230, 2023). "miR-34a directly regulates SIRT1, which is a molecule that regulates insulin release in the beta pancreatic cells that are damaged in diabetes." (PMID 37927446, 2023). "Autophagosome formation and mitophagy flux were decreased significantly in the retina from mice in WT-D group, compared to WT-N group, and Sirt1 overexpression ameliorated diabetes-induced decrease in autophagosomes and mitophagy flux." (PMID 37415667, 2023). "As a result, SIRT1 is a promising therapeutic target for the treatment of insulin resistance and diabetes." (PMID 37089941, 2023). "These functions are similar to its basic mechanism of anti-diabetes and are related to activating SIRT1 and insulin-related signaling pathways." (PMID 37009462, 2023). "Similar phenomenon is observed in the retina of diabetic mice where overexpression of Sirt1 ameliorates diabetes-induced decrease in the GTPase activity of Mfn2, and the formation of autophagosomes for the removal of the damaged mitochondria." (PMID 37415667, 2023). "Experimental studies have found that the development of diabetes‐related cognitive impairment is closely related to SIRT1, one of the modulators of insulin resistance that plays an important role in learning and memory." (PMID 37248634, 2023). "As a peroxisome-proliferator-activated receptor agonist, the protective effect of Fenofibrate in the diabetes-induced cardiac remodeling was depended on FGF21- Sirtuin-1 (SIRT1) activated autophagy." (PMID 37416922, 2023). "Activation of DNA methylation machinery in diabetes downregulates retinal Mfn2 gene transcripts, and here we show that Sirt1 inhibition leaves it hyperacetylated with reduction in its GTPase activity." (PMID 37415667, 2023).
diabetes (continued). "Our findings demonstrated that diabetes elevated miR-34a, which in turn decreased SIRT1’s expression levels as its target gene." (PMID 38129872, 2023). "Increased mTOR activity and decreased expression of AMPK and silent information regulator of transcription 1 (Sirt1) in diabetes can inhibit autophagy to aggravate cellular dysfunction and the progression of DN." (PMID 37020591, 2023). "In studies using a mouse model of diabetes, curcumin administration modulated SIRT1 through AMPK, leading to improved glucose absorption and metabolism." (PMID 37630770, 2023). "Similar phenomenon was observed in diabetic mice; overexpression of sirtuin 1 (a deacetylase) ameliorated diabetes-induced inhibition of retinal Mfn2 and facilitated the removal of the damaged mitochondria." (PMID 37415667, 2023). "Diabetes induced the declined expression of SIRT1 in the cardiac tissues, which was reversed by YNJ administration." (PMID 37288289, 2023). "In conclusion, the improvement effect of RES on diabetes is related to the activation of SIRT1 and insulin-related signaling pathways, thereby inhibiting inflammation and oxidative stress, and improving mitochondrial function." (PMID 37009462, 2023). "Silent Information Regulator 1 (SIRT1) has also been identified as a master regulator in endocrine and metabolic diseases, such as hyperuricemia, diabetes, hypertension, hyperlipidemia, osteoporosis, and polycystic ovary syndrome." (PMID 37834287, 2023). "Sirutin1 (Sirt1) is one of the deacetylating enzymes responsible for maintaining acetylation status of proteins, and in diabetes, its expression and activity are decreased in the retina and its capillary cells." (PMID 37415667, 2023). "SIRT1 plays a key role in preventing diabetes-induced cardiac inflammation, oxidative stress, and dysfunction." (PMID 36843938, 2023). "Our results suggest that QCSPIONs can regulate the SIRT1/p66Shc-mediated signaling pathway and can be considered a promising candidate for ameliorating the complications of diabetes." (PMID 38129872, 2023). "According to the results of this study, AME has beneficial effects on protecting against diabetes-related aberrant peripheral energy metabolism through activation of the PGC1α/SIRT1-dependent mechanism by FGF21." (PMID 37299522, 2023). "For instance, hsa_circ_0115355 has been found to regulate activity of miR-145/SIRT1 axis, thus enhancing function of pancreatic ß cells in patients with type 2 diabetes mellitus." (PMID 37441551, 2023). "It was indicated that overexpression of SIRT1 in podocytes attenuates proteinuria and kidney injury in an animal model of diabetes." (PMID 35721758, 2022). "Remarkably, in DKD, SIRT1 activation exerted a protective effect on the kidney in several models of renal injury, whereas the elimination of SIRT1 exacerbated renal alterations in diabetes." (PMID 35277012, 2022). "SIRT1 is closely related to aging-related diseases, diabetes, vascular diseases and kidney diseases, and widely involved in the regulation of various intracellular processes, including apoptosis, metabolism and autophagy." (PMID 35721758, 2022). "Forkhead-box class O, SIRT1, inflammation, and metabolism play important roles in regulating aging and various diseases such as cancer and diabetes." (PMID 36430361, 2022). "In a diabetes animal model, SIRT1 was expressed in pancreatic β-cells and increased insulin secretion in response to glucose." (PMID 35469171, 2022).